SNX1 (sorting nexin 1)
Description:
Involved in several stages of intracellular trafficking. Interacts with membranes containing phosphatidylinositol 3-phosphate (PtdIns(3P)) or phosphatidylinositol 3,5-bisphosphate (PtdIns(3,5)P2). Acts in part as component of the retromer membrane-deforming SNX-BAR subcomplex. The SNX-BAR retromer mediates retrograde transport of cargo proteins from endosomes to the trans-Golgi network (TGN) and is involved in endosome-to-plasma membrane transport for cargo protein recycling. The SNX-BAR subcomplex functions to deform the donor membrane into a tubular profile called endosome-to-TGN transport carrier (ETC) (Probable). Can sense membrane curvature and has in vitro vesicle-to-membrane remodeling activity. Involved in retrograde endosome-to-TGN transport of lysosomal enzyme receptors (IGF2R, M6PR and SORT1) and Shiginella dysenteria toxin stxB. Plays a role in targeting ligand-activated EGFR to the lysosomes for degradation after endocytosis from the cell surface and release from the Golgi. Involvement in retromer-independent endocytic trafficking of P2RY1 and lysosomal degradation of protease-activated receptor-1/F2R. Promotes KALRN- and RHOG-dependent but retromer-independent membrane remodeling such as lamellipodium formation; the function is dependent on GEF activity of KALRN. Required for endocytosis of DRD5 upon agonist stimulation but not for basal receptor trafficking.
Synonyms: SNX1A; MGC8664; HsT17379; Vps5
Tractability: Small molecule: it has a binding pocket of medium quality. Antibody: UniProt places it where antibodies can reach, with high confidence. PROTAC: ubiquitination databases record sites on it; its protein half-life has been measured.
Gene: Protein-coding gene on chromosome 15 (64,094,123 to 64,146,090, forward strand). Ensembl gene ENSG00000028528.
Subcellular location: Endosome membrane; Golgi apparatus, trans-Golgi network membrane; Early endosome membrane; Cell projection, lamellipodium
Subcellular location (Human Protein Atlas): Endosomes; Lysosomes
Gene Ontology:
Molecular function: cadherin binding; epidermal growth factor receptor binding; identical protein binding; insulin receptor binding; leptin receptor binding; phosphatidylinositol binding; protein binding; protein heterodimerization activity; protein homodimerization activity; transferrin receptor binding
Biological process: early endosome to Golgi transport; endosome membrane tubulation; intracellular protein transport; lamellipodium morphogenesis; receptor internalization; retrograde transport, endosome to Golgi; endosomal transport; intercellular transport; positive regulation of protein catabolic process
Cellular component: cytoplasm; early endosome membrane; endosome; endosome membrane; lysosome; membrane; protein-containing complex; retromer complex; retromer, tubulation complex; vesicle; cytosol; early endosome; Golgi apparatus; lamellipodium
Genetic constraint (gnomAD): Loss-of-function variants: 23 observed, 48.86 expected, observed/expected ratio (o/e) 0.47, 90% interval 0.34 to 0.67. The upper end of that interval is the gene's LOEUF score, 0.67, which puts it in group 2 of 6, group 1 being the genes least tolerant of losing a copy. Missense variants: 495 observed, 542.23 expected, observed/expected ratio (o/e) 0.91, 90% interval 0.85 to 0.98. Synonymous variants: 222 observed, 208.27 expected, observed/expected ratio (o/e) 1.07, 90% interval 0.95 to 1.19.
Homologues: Orthologues: chimpanzee SNX1 (98% identical), pig SNX1 (97% identical), macaque SNX1 (96% identical), guinea pig SNX1 (95% identical), dog SNX1 (95% identical), rat LOC102549158 (95% identical), mouse Snx1 (95% identical), rabbit SNX1 (93% identical), zebrafish snx1a (71% identical), zebrafish SNX1 (58% identical), tropical clawed frog snx1 (58% identical). Paralogues in human: SNX2 (60% identical), SNX18 (19% identical), SNX7 (18% identical), SNX30 (17% identical), SNX33 (17% identical), SNX32 (16% identical), SNX4 (16% identical), SNX5 (15% identical), SNX6 (15% identical), SNX9 (15% identical), SNX8 (14% identical), SNX11 (12% identical), and 3 more.
Diseases named in the same sentence as SNX1 in open-access papers:
SNX1 is named in the same sentence as 33 diseases in open-access papers, as found by Europe PMC text mining. Sharing a sentence is not in itself a finding about the gene and the disease. The quoted sentences say what the papers report.
lung carcinoma (6 papers, 2015 to 2024). "This review focused on the mechanism for EGFR endocytosis associated with SNX1 trafficking in gefitinib-resistant lung cancer cells." (PMID 35582586, 2019). "This review will mostly focus on the mechanism for EGFR endocytosis regulated by SNX1 trafficking in gefitinib-resistant human lung cancer cells." (PMID 35582586, 2019). "Lung cancer cells exhibit hyperphosphorylation of the corresponding serine in SNX1, SNX2, SNX3, and SNX2136,39." (PMID 29520003, 2018). "Consequently, it was inferred that membrane trafficking of EGFR may be significantly perturbed in gefitinib-resistant cells, and that the trafficking machinery of SNX1 may play a suppressive function in regulating EGFR endocytosis in human lung cancer cells." (PMID 35582586, 2019). "Studies using siRNA-mediated down-regulation of SNX1 and SNX2 suggest their involvement in regulating MET signaling in lung cancer cells." (PMID 38836326, 2024). "SNX1 is also reported to suppress EGFR membrane recycling and activate EGFR/PI3K/AKT signaling pathway in lung cancer cells." (PMID 29868263, 2018). "Mechanistic investigation showed that miR-95 suppresses expression of SNX1 by directly targeting its 3′ UTR in colorectal and lung cancer cells." (PMID 25971210, 2015).
non-small cell lung carcinoma (6 papers, 2016 to 2025). A group of at least three distinct histological types of lung cancer, including non-small cell squamous cell carcinoma, adenocarcinoma, and large cell carcinoma. "For instance, studies has demonstrated that SNX1 expression is dramatically decreased in colorectal as well as non-small cell lung cancer cells, and it is crucial to the pathogenesis of these tumors." (PMID 40421300, 2025). "In gefitinib-resistant non-small cell lung cancer cells, SNX1 was found to inhibit the endocytosis and degradation of MET whose overexpression was believed to be responsible for gefitinib resistance in non-small cell lung cancer." (PMID 35715463, 2022). "Downregulation of SNX1 by microRNA-95 was reported to induce proliferation in non-small cell lung cancer." (PMID 29868263, 2018). "Several studies suggest that SNX1 may function as a tumor suppressor in colorectal and non-small cell lung cancer (NSCLC)." (PMID 29954076, 2018). "SNX1 were shown to induce chemoresistance in non-small cell lung cancer." (PMID 29868263, 2018).
colon cancer (5 papers, 2018 to 2025). "Then, miR-95 was found to bind to the 3'untranslated region of SNX1, and promoted proliferation of colon cancer cells caused by miR-95 overexpression could be reversed by SNX1 overexpression, suggesting that miR-95 alleviated anticancer effect of SNX1 in colon cancer." (PMID 35715463, 2022). "Some members, such as SNX1, SNX6, and SNX27, have oncogenic properties, promoting proliferation and metastasis by activating the TGF-β signaling pathway and recycling cancer-associated proteins in gastric, pancreatic, and colon cancer, respectively." (PMID 40810725, 2025). "SNX1 expression is significantly downregulated in colon cancer." (PMID 35024436, 2022). "In a study of 20 colon cancer patients, 75% had significantly less SNX1 protein expression compared to matched adjacent normal controls while a separate cohort of patients showed decreased SNX1 mRNA in 18 of 19 tumor samples." (PMID 29954076, 2018). "Downregulation of SNX1 was first reported in human colon cancer (Holdren, Her & Parks, 2005)." (PMID 29868263, 2018). "Knockdown of SNX1 expression can significantly increase the phosphorylation level of epidermal growth factor receptor (EGFR) and promote colon cancer cell proliferation." (PMID 35024436, 2022).
colorectal cancer (5 papers, 2018 to 2026). A primary or metastatic malignant neoplasm that affects the colon or rectum. "Given SNX1’s previously reported tumor-suppressive role in colorectal cancer and its consistent downregulation in OV, SNX1 was selected for further investigation." (PMID 41487280, 2026). "Specifically, strong evidence points to the involvement of sorting nexins (SNXs), particularly SNX1 and SNX2, in the signaling and trafficking of the receptor tyrosine kinase (RTK) MET in colorectal cancer (CRC)." (PMID 38836326, 2024). "Among them, sorting nexin 1 (SNX1) was first identified as a protein interacting with the epidermal growth factor receptor (EGFR) and has since been reported to act as a tumor suppressor in various cancers, including lung, gastric, and colorectal cancers." (PMID 41487280, 2026).
gastric cancer (5 papers, 2018 to 2024). A primary or metastatic malignant neoplasm involving the stomach. "SNX1 was lower expressed in gastric cancer, but its lower expression associated with longer survival time." (PMID 35715463, 2022). "Our study also indicated that SNX1 was associated with EMT in gastric cancer cells as it showed that overexpression of SNX1 in GC cells inhibited migration and invasion, and led to upregulation of E-cadherin and downregulation of Vimentin and Snail." (PMID 29868263, 2018). "SNX4/5/6/7/8/10/13/14/15/16/20/22/25/27/30 were overexpressed in gastric cancer, while SNX1/17/21/24/33 were higher expressed in normal tissue." (PMID 35715463, 2022). "Therefore, a novel role for SNX1 as a putative tumor suppressor marker in gastric cancer, possibly via EMT regulation, has been suggested." (PMID 36612066, 2022). "Sorting nexin-1 (SNX1) is an important functional protein in cell endocytosis, efflux, protein sorting, cell signal transduction, etc; however, the expression, the role and clinical relevance of SNX1 have not been investigated in gastric cancer (GC)." (PMID 29868263, 2018).
dementia (2 papers, 2022 to 2025). Loss of intellectual abilities interfering with an individual's social and occupational functions. "As mentioned in the Results section, this second cluster includes genes that have also been related to other dementia types (e.g., GRN, TMEM107B, SNX1, MAPT, CTSB and CTSH)." (PMID 36066633, 2022).
iron deficiency (2 papers, 2016 to 2017). "For SNX1, for example, we have recently reported that its protein levels are increased under iron deficiency conditions." (PMID 27725825, 2016). "Consistent with this, a SNX1-dependent IRT1 endosomal recycling in the epidermis has been shown to be crucial for IRT1 localization at the plasma membrane under iron deficiency." (PMID 27725825, 2016). "The fusion was shown to complement both the auxin- and iron deficiency-related SNX1 loss-of-function phenotypes." (PMID 27725825, 2016). "The upregulation of SNX1 gene is consistent with the previously observed increased abundance of SNX1-GFP protein under iron deficiency." (PMID 27725825, 2016). "The levels of SNX1 in response to iron deficiency are upregulated in the cells of the central cylinder." (PMID 27725825, 2016). "We could also observe zone-specific transcriptional changes of SNX1 under iron deficiency, which are consistent with the described role of the SNX1 protein." (PMID 27725825, 2016). "In the absence of the endosomal sorting protein SORTING NEXIN 1 (SNX1), the principal iron transporter IRT1 fails to recycle and is instead degraded, leading to failure of snx1 mutant plants to cope with iron deficiency." (PMID 29033955, 2017).
Alzheimer disease (1 paper, 2009). A progressive, neurodegenerative disease characterized by loss of function and death of nerve cells in several areas of the brain leading to loss of cognitive function such as memory and language. "Depletion in humans of other, related, retromer subunits, Vps26 and Vps35, which require either SNX1 or SNX2 in order to associate with endosomes, increases amyloid-β peptide production associated with Alzheimer's disease." (PMID 19309515, 2009).
glioma (1 paper, 2015). A benign or malignant brain and spinal cord tumor that arises from glial cells (astrocytes, oligodendrocytes, ependymal cells). "Among these 4 proteins, SNX1 and IGHG1 were up-regulated in gliomas, while, PQBP1 and EYA1 were down-regulated in gliomas." (PMID 26370624, 2015). "However, there were no common proteins which were differentially expressed in Grade II and IV with the exception of 4 proteins, SNX1, EYA1, PQBP1, and IGHG1, which were dysregulated across all the grades of gliomas." (PMID 26370624, 2015). "Our studies have shown that the SNX1 protein is up-regulated in gliomas and we could not find differential expression of EGFR in gliomas." (PMID 26370624, 2015).
Hypertension (1 paper, 2018). The presence of chronic increased pressure in the systemic arterial system. "Besides above, SNX1 is associated with some other pathologies including bacterial infection and hypertension." (PMID 29868263, 2018).
lymph node metastasis (1 paper, 2018). "We found in the 90 patient with GC that SNX1 was associated with lymph node metastasis (p = 0.0286)." (PMID 29868263, 2018). "In this study, we also found that low-level SNX1 was associated with lymph node metastasis, and patients with high-level SNX1 maintained a higher survival rate." (PMID 29868263, 2018).
melanoma (1 paper, 2025). A malignant, usually aggressive tumor composed of atypical, neoplastic melanocytes. "The results showed upregulation of NR1H3, NTHL1, and SNX1, and downregulation of DSP in melanoma compared to normal skin." (PMID 41573564, 2025).
meningioma (1 paper, 2017). A generally slow growing tumor attached to the dura mater. "The trends of gene expression profiles of candidates such as EFCAB2, EPS8L1, NOL3, PAIP1 and SNX1 showed elevated expression in meningiomas compared to controls, while CAMK2N1, CRYM and PRPSAP2 showed decreased expression levels in meningiomas compared to the controls." (PMID 28938569, 2017).
osteosarcoma (1 paper, 2023). A usually aggressive malignant bone-forming mesenchymal neoplasm, predominantly affecting adolescents and young adults. "To this end, we performed double knockout (KO) of SNX1 and SNX2 (SNX1-2), and SNX5 and SNX6 (SNX5-6), in the human osteosarcoma cell line HT1080." (PMID 37322239, 2023).
ovarian carcinoma (1 paper, 2026). A malignant neoplasm originating from the surface ovarian epithelium. "In this study, we revealed that SNX1 is significantly downregulated in ovarian cancer and correlates with poor prognosis and reduced sensitivity to chemotherapeutic agents such as paclitaxel, docetaxel, and 5-fluorouracil." (PMID 41487280, 2026). "Collectively, these findings suggest that SNX1 exerts tumor-suppressive effects in ovarian cancer by promoting apoptosis and inhibiting migration, potentially through the disruption of EMT-associated pathways." (PMID 41487280, 2026). "The functional role of SNX1 in ovarian cancer progression was further assessed using A2780 and HEY cell lines with SNX1 overexpression." (PMID 41487280, 2026). "These limitations highlight the need for future studies employing more representative and genetically defined models—such as patient-derived organoids or single-cell profiling—to better understand the context-specific role of SNX1 in ovarian cancer." (PMID 41487280, 2026). "Sorting nexin 1 (SNX1), a member of the sorting nexin family, has been implicated in various cellular processes, yet its role in ovarian cancer (OV) remains poorly characterized." (PMID 41487280, 2026). "In conclusion, our study provides strong evidence that SNX1 functions as a tumor suppressor in ovarian cancer by negatively regulating the CDK–Rb–E2F axis, suppressing EMT and enhancing paclitaxel sensitivity." (PMID 41487280, 2026). "To examine whether SNX1 expression differs among ovarian cancer subtypes, we analyzed multiple transcriptomic datasets and observed notable differences between HGSOC and OCCC." (PMID 41487280, 2026). "Inherent genetic variations among different ovarian cancer cell lines may modulate the cellular response threshold to SNX1 signaling or the sensitivity of its downstream effectors." (PMID 41487280, 2026). "However, the role of SNX1 in ovarian cancer remains largely unexplored." (PMID 41487280, 2026). "It is noteworthy that the phenotypic potency induced by SNX1 overexpression—such as the inhibition of proliferation and the sensitivity to paclitaxel—did not exhibit a simple linear correlation with its protein expression levels in the two ovarian cancer cell lines (A2780 and HEY)." (PMID 41487280, 2026). "Furthermore, investigating the potential crosstalk between SNX1 and other SNX family members in the tumor microenvironment could provide a more comprehensive understanding of the SNX protein network in ovarian cancer pathogenesis and therapy resistance." (PMID 41487280, 2026).
serous ovarian carcinoma (1 paper, 2026).
skin tumor (1 paper, 2014). "Additional studies will be required to determine whether the amino acid variant at position 117 in the mouse SNX1 protein has a similar effect and if this variant plays a role in skin tumor promotion susceptibility." (PMID 24700353, 2014).
triple-negative breast carcinoma (1 paper, 2024). An invasive breast carcinoma which is negative for expression of estrogen receptor (ER), progesterone receptor (PR), and human epidermal growth factor receptor 2 (HER2). "Prior work identified a cell-permeable peptide termed SNX1.3, derived from the BAR domain of sorting nexin 1 (SNX1), that potently blocks the retrograde and nuclear trafficking of EGFR in triple negative breast cancer cells." (PMID 38909779, 2024).
ZIKV infection (1 paper, 2023). "Snx1 was also observed to be differentially upregulated in EVs secreted by ZIKV-inoculated trophoblast cells in a macaque ZIKV infection model of pregnancy." (PMID 37781396, 2023).